B4GALT3 (beta-1,4-galactosyltransferase 3)
Diseases named in the same sentence as B4GALT3 in open-access papers:
B4GALT3 is named in the same sentence as 23 diseases in open-access papers, as found by Europe PMC text mining. Sharing a sentence is not in itself a finding about the gene and the disease. The quoted sentences say what the papers report.
liver cancer (7 papers, 2018 to 2023). An epithelial or non-epithelial malignant neoplasm that arises from the liver. "Recent studies have shown that B4GALT3 is associated with glioblastoma, colorectal cancer, cervical cancer, bladder cancer, and lung metastasis with liver cancer." (PMID 37901252, 2023). "Liver cancer cell-derived exosomes transfer miR-1247-3p to recipient cells and induce CAFs by targeting B4GALT3, eventually leading to lung dissemination." (PMID 33741023, 2021). "In sum, our results show that, tumor-derived exosomal miR-1247-3p converts fibroblasts to CAFs via downregulating B4GALT3, to activate β1-integrin–NF-κB signaling pathway to promote lung metastasis of liver cancer." (PMID 29335551, 2018). "In liver cancer, tumor-derived exosomes transfer miR-1247-3p from donor cells to recipient cells and induces CAFs activation by targeting B4GALT3, finally leading to lung dissemination." (PMID 30154401, 2018). "In conclusion, our results indicate that tumor-derived exosomal miR-1247-3p converts fibroblasts to CAFs by decreasing B4GALT3, to activate β1-integrin–NF-κB signaling pathway in lung pre-metastatic niche from liver cancer." (PMID 29335551, 2018). "In addition, the knockdown of B4GALT3 promoted fibroblast motility and led to an activation of β1-integrin-NF-κB signaling in fibroblasts, further promoting liver cancer progression by secreting interleukin (IL)-6 and IL-8." (PMID 30312173, 2018). "B4GALT2, B4GALT3, DPM1, DPM2, HS2ST1, and PIGS are unfavorable prognostic markers in liver cancer according to the analysis by human protein atlas." (PMID 32850363, 2020).
hepatocellular carcinoma (6 papers, 2018 to 2022). A malignant tumor that arises from hepatocytes. "Moreover, previous studies have shown that highly metastatic hepatocellular carcinoma (HCC) cells secrete exosomal miR-1247-3p targeting B4GALT3, leading to activation of β1-integrin-NF-kB signaling in fibroblasts." (PMID 30309355, 2018). "Likewise, in the lung metastatic niche, high-metastatic hepatocellular carcinoma cells typically exhibited great ability to convert normal fibroblasts into CAFs, which was mediated by exosomal miR-1247-3p derived from HCC cells that activated CAFs via the B4GALT3-β1-integrin-NF-κB axis." (PMID 36324128, 2022).
neuroblastoma (6 papers, 2016 to 2023). Neuroblastoma (NB) is the most common solid, extracranial childhood tumor. "The expression of B4GALT3 enhanced migration and invasion of human neuroblastoma cells, and highly expression of B4GALT4 was associated with colorectal cancer metastasis and poor prognosis." (PMID 27092876, 2016). "B4GALT3 is differentially expressed in tumors and adjacent normal tissues, and is correlated with clinical prognosis in several cancers, including neuroblastoma, cervical cancer, and bladder cancer." (PMID 37901252, 2023). "Research has highlighted the involvement of B4GALT3 in the proliferation, invasion and metastasis of cervical cancer, neuroblastoma, and colon cancer cells." (PMID 36263426, 2022). "In neuroblastoma, overexpression of B4GALT3 increased migration, invasion, and tumor growth of neuroblastoma cells, and B4GALT3 expression was correlated with advanced clinical stages, unfavorable Shimada histology, and lower survival rate." (PMID 30312173, 2018).
bladder cancer (5 papers, 2018 to 2025). "For instance, our previous study found that circUBXN7 expression was downregulated in bladder cancer, and forced circUBXN7 expression could suppress cell growth and invasion by sponging miR-1247 to enhance B4GALT3 expression in bladder cancer cells." (PMID 34911533, 2021). "This tumor-restricted expression pattern may be explained by the upregulation of B4GALT3 and B4GALT4, as shown in the TCGA bladder cancer dataset." (PMID 40706589, 2025). "To explore the role of B4GALT3 in the TIME, we first investigated the growth of four C57BL/6 strain tumor models with varying immunogenicity: breast adenocarcinoma E0771, colon carcinoma MC38, melanoma B16F10, and bladder carcinoma MB49." (PMID 37901252, 2023).
cervical cancer (5 papers, 2018 to 2024). A primary or metastatic malignant neoplasm involving the cervix. "The B4GALT3 gene is upregulated in glioblastoma and cervical cancer and is considered to be related to tumor cell proliferation and invasion, suggesting a poor prognosis." (PMID 38244579, 2024). "Moreover, B4GALT3 enhanced β1-integrin stability and contributed to the oncogenic activity in cervical cancer cells." (PMID 30312173, 2018).
breast cancer (4 papers, 2015 to 2024). A primary or metastatic malignant neoplasm involving the breast. "Through its effect on B4GALT3, miR-1247-3p activates the β1 integrin-NF-κB signaling pathway in fibroblasts, thereby promoting the migration and invasion of breast cancer (BC) cells." (PMID 39739897, 2024). "B4galt4 is most homologous to the B4galt3 gene, and the growth of the strongly immunogenic E0771 breast cancer cell line in B4galt4 KO mice was unaffected." (PMID 37901252, 2023). "Further, both in ovarian and ER−/HER2- breast cancer patients, a co-expression pattern for UBE2Q1 alongwith B4GALT3 was observed suggesting a functional interaction and potential pathological contribution of these two genes in the cancer subtypes." (PMID 33663405, 2021). "We also evaluated for the consequence of high expression of B4GALT3 on breast cancer patient survival and alike ovarian cancer, no significant adverse effect was observed for breast cancer patients expressing high B4GALT3." (PMID 33663405, 2021). "We have observed differential overexpression of B4GALT3 and also a co-expressional pattern with UBE2Q1, however it does not correlate with ovarian and breast cancer prognosis." (PMID 33663405, 2021).
colorectal cancer (4 papers, 2014 to 2023). A primary or metastatic malignant neoplasm that affects the colon or rectum. "The same research team has recently published that β-1,4-galactosyltransferase III (B4GALT3) overexpression in colorectal cancer cells suppressed cell migration, invasion, and adhesion, while B4GALT3 knockdown enhanced malignant cell phenotypes promoting cell migration and invasion." (PMID 25120952, 2014). "Besides, B4GALT3 overexpression suppressed cell migration, invasion and adhesion in colorectal cancer (CRC), and B4GALT3 was negatively correlated with poorly differentiated histology, advanced stages, regional lymph node metastasis and distant metastasis in CRC patients." (PMID 30312173, 2018).
glioblastoma (3 papers, 2021 to 2024). The most malignant astrocytic tumor (WHO grade IV). "Even in glioblastoma, overexpression of B4GALT3 is associated with poor prognosis of patients and suggest this protein as oncogenic in nature." (PMID 33663405, 2021).
acute lymphoblastic leukemia (1 paper, 2018). Leukemia with an acute onset, characterized by the presence of lymphoblasts in the bone marrow and the peripheral blood. "For example, B4GALT3 was significantly overexpressed in dup (1q)-positive acute lymphoblastic leukemias (ALLs) compared with high hyperdiploid ALLs without dup (1q)." (PMID 30312173, 2018).
adenomyosis (1 paper, 2025). The growth of endometrial tissue inside the muscular wall of the uterine corpus. "Notably, B4GALT3 was robustly expressed in the eutopic endometrium of adenomyosis patients but was almost undetectable in healthy endometrium." (PMID 41356013, 2025).
female reproductive cancers (1 paper, 2021). "By performing genome wide expression analysis of tumor samples of high grade serous ovarian cancer patients and generating co-expression patterns of differentially expressed genes (DEGs), we found UBE2Q1 - B4GALT3 axis as an important player in female reproductive cancers." (PMID 33663405, 2021).
ovarian carcinoma (1 paper, 2021). A malignant neoplasm originating from the surface ovarian epithelium. "Our study identifies a potential UBE2Q1 – B4GALT3 functional axis in ovarian cancer, where only the E2 conjugating enzyme showed a poor prognostic impact on the disease." (PMID 33663405, 2021). "We also propose, a UBE2Q1 – B4GALT3 axis, co-relative overexpression of which is envisaged to have an oncogenic potential in ovarian cancer development." (PMID 33663405, 2021). "To investigate the potential of UBE2Q1 and B4GALT3 as prognostic markers, we performed survival analysis on these genes to identify their effects on relapse free survival of ovarian cancer patients." (PMID 33663405, 2021). "Thus, our study identifies a potential UBE2Q1 – B4GALT3 functional axis in breast and ovarian cancer, where only the E2 conjugating enzyme showed a poor prognostic impact on the disease." (PMID 33663405, 2021). "Thus, it would be interesting to investigate exact function of B4GALT3 in ovarian cancer in future." (PMID 33663405, 2021). "Thus, we infer that although B4GALT3 has no impact on ovarian cancer prognosis, its potential oncogenic function could not be excluded and would need further investigation." (PMID 33663405, 2021).
skin cutaneous melanoma (1 paper, 2023). "B4GALT3 expression was higher in metastatic skin cutaneous melanoma (SKCM-metastasis) than in primary skin cutaneous melanoma (SKCM-Primary)." (PMID 37901252, 2023).
cancer (16 papers, 2015 to 2025). A tumor composed of atypical neoplastic, often pleomorphic cells that invade other tissues. "Integrin β1 is so far the only reported substrate of B4GALT3, and impaired expression of B4GALT3 in tumors causes modifications in the behavior of cancer cells." (PMID 37355744, 2023). "For example, exosomal miR-1247-3p secreted by high-metastatic HCC converts fibroblasts to cancer-associated fibroblasts (CAFs) to form PMNs by directly targeting B4GALT3 and activating β1-integrin-NF-κB signaling." (PMID 37781522, 2023). "B4GALT3 is associated with prognosis and proliferation in various cancers." (PMID 37901252, 2023). "Specifically, related to this pathway, we observed down-regulation of genes such as b4galt3, st3gal1, and a notable 5-fold increase in b3gnt7 expression, a combination that is consistent with current metastasis literature in many cancer types." (PMID 40719625, 2025). "B4GALT3 is an enzyme in charge of the production of poly-N-acetyllactosamine and plays a crucial role in the occurrence, development, and metastasis of cancers." (PMID 38244579, 2024). "The controversial roles of B4GALT3 in human cancers compelled us to elucidate its biological function in BC." (PMID 30312173, 2018). "B4GALT3 might be suppressing cancer immunity by synthesizing the glycan structure of molecules on the CD8+ T cell surface, as evidenced by the changes in the glycan structure of ITGAL in immune cells." (PMID 37901252, 2023). "Furthermore, the B4galt3 KO mouse generated in our study offers a valuable tool for future research on the complex interactions between glycosylation and immune responses in cancer." (PMID 37901252, 2023). "B4GALT3 has been reported to play different roles in different diseases including human cancers." (PMID 30312173, 2018). "First, we confirmed that B4GALT3 expression could be downregulated in MRC5 by miR-1247-3p or exosomes derived from high-metastatic cancer cells at both mRNA and protein levels." (PMID 29335551, 2018). "Similarly, the luciferase activity remarkedly decreased only in MRC5 transfected with wild-type binding site vector of B4GALT3 after treatment with high-metastatic cancer cell-derived exosomes." (PMID 29335551, 2018). "Moreover, TME-fibroblasts are activated (cancer-associated fibroblasts (CAFs)) in highly malignant HCC, with an increased metastatic behavior via HCC-derived miR-1247-3p that alters the expression (decrease) of Beta-1,4-Galactosyltransferase 3 (B4GALT3)." (PMID 40650114, 2025). "However, whether B4GALT3 is important in cancer or immune cells cannot be determined from these findings." (PMID 37901252, 2023). "The elevated expression of B4GALT3 in multiple tumor types, including ACC, CESC, LIHC, MESO, SARC, and HNSC, underscores its potential as a biomarker for these cancers." (PMID 37901252, 2023). "This investigation aimed to elucidate the function of B4GALT3 in the TIME, and determine its potential clinical implications for cancer therapy." (PMID 37901252, 2023). "In addition, we found that MAN1A1 and MAN2C1 are downregulated in most cancer types, whereas B4GALT1 and B4GALT3–5 are upregulated in most cancer types." (PMID 41093273, 2025). "However, the degree of staining in DPM1, B4GALT3, B4GALT2, and B4GALNT1 was stronger in cancer tissues than normal tissues." (PMID 35356430, 2022). "Indeed, several glycosylation factors, namely ALG8, ALG3, COLGATLT1, B4GALT3 and DPM2, show increased expression levels in these and other cancers." (PMID 36009354, 2022). "Importantly, B4galt3 KO mice showed no adverse effects on growth, development, or reproduction, underscoring the potential of B4GALT3 as a promising and safe therapeutic target for cancer treatment." (PMID 37901252, 2023).
tumor (10 papers, 2018 to 2026). "The risk score of all tumor samples was counted as follows: Risk score = (0.974* B4GALT3) + (0.418* PYGL) + (0.195* GALNT14) + (−0.413* FUT2) + (−0.886* GALNT16)." (PMID 38244579, 2024). "Our study demonstrates that B4galt3 deficiency can potentially boost anti-tumor immune responses, largely through enhancing the influx of CD8+ T cells." (PMID 37901252, 2023). "After CD8+ T cells in mice were depleted using an anti-CD8 antibody, B4galt3 KO mice did not respond to the growth inhibition of tumors with strong immunogenicity, demonstrating that CD8+ T cells are essential for suppressing tumor growth by B4galt3 deficiency." (PMID 37901252, 2023). "Recent studies have shown that B4GALT3 is associated with tumor proliferation and metastasis." (PMID 37901252, 2023). "Finally, silencing of B4GALT3 promoted proliferation and invasion of BC cells; and partially abolished the tumor suppressive effects caused by circUBXN7." (PMID 30312173, 2018). "Genetic modulation of B4GALT3 significantly altered both tumor burden and invasive behavior in orthotopic xenograft models." (PMID 41866544, 2026). "Specifically, we observed that genes participating in the N-glycosylation pathway such as MAN1A1, MGAT1, FUT8, and B4GALT3 were significantly upregulated in neoplasia when compared with healthy subjects." (PMID 40087977, 2025). "And because in the RNA-seq analysis of tumor-infiltrating CD8+ T cells, B4galt3 deficiency was positively associated with integrin-mediated cell adhesion." (PMID 37901252, 2023). "We examined the growth of various strongly or weakly immunogenic tumor cell lines transplanted into B4galt1, B4galt3, and B4galt4 knockout (KO) mice." (PMID 37901252, 2023). "In conclusion, our study provides new insights into the role of B4GALT3 in mediating tumor-immune interactions." (PMID 37901252, 2023). "Bone marrow transplantation and CD8+ T cell depletion experiments were conducted to elucidate the role of immune cells in suppressing tumor growth in B4galt3 KO mice." (PMID 37901252, 2023). "Mechanistically, circUBXN7 serves as a tumor suppressor by sponging miR-1247-3p to upregulate B4GALT3 in BC." (PMID 30312173, 2018). "We further demonstrated that circUBXN7 was a tumor suppressor in BC by sponging miR1247-3p and upregulating B4GALT3 expression." (PMID 30312173, 2018). "For example, B4GALT3 knockout mice demonstrated inhibited growth of highly immunogenic tumors accompanied by a significant elevation in the infiltration of CD8 T cells within the tumor microenvironment." (PMID 38244579, 2024). "Given the pivotal role of CD8+ T cells in anti-tumor activity, we sought to determine whether the tumor suppression observed in B4galt3 KO is dependent on CD8+ T cells." (PMID 37901252, 2023). "The increase in FAK phosphorylation in B4galt3 KO T cells could therefore reflect enhanced T cell activation, potentially contributing to the increased anti-tumor activity in B4galt3 KO mice." (PMID 37901252, 2023). "We performed BM transplantation experiments to examine whether immune cells from the BM played a role in tumor growth suppression in B4galt3 KO mice." (PMID 37901252, 2023). "Then, we identified that miR-1247-3p was directly transferred from tumor cells to fibroblasts in lung pre-metastasis niche via exosomes and converts fibroblasts to CAFs by decreasing its target B4GALT3 expression to activate β1-integrin–NF-κB signaling pathway." (PMID 29335551, 2018). "Therefore, B4GALT3 controls tumor growth through the immune system." (PMID 37901252, 2023). "We further investigated whether B4GALT3 controls tumor growth by modulating the immune system." (PMID 37901252, 2023). "Furthermore, analysis of the expression of human B4GALT3 mRNA in TCGA database revealed that B4GALT3 was differentially expressed between tumor tissues and normal tissues, and the expression of B4GALT3 was related to the prognosis of ACC, CESC, LIHC, MESO, SARC, and HNSC." (PMID 37901252, 2023).
tumor (continued). "However, the exact role of B4GALT3 in the tumor immune microenvironment (TIME) remains unclear." (PMID 37901252, 2023). "In cervical epithelial cancer, overexpression of B4GALT3 is observed which increases migration, invasion and EMT of tumor cells." (PMID 33663405, 2021). "In our study, we confirmed that silencing of B4GALT3 significantly enhanced cell viability and invasive capacity, indicating that B4GALT4 exerted a tumor suppressive role in BC." (PMID 30312173, 2018). "WT mice transplanted with B4galt3 KO BM cells, but not WT BM cells, showed suppressed tumor growth, indicating that immune cells are crucial." (PMID 37901252, 2023). "In mice with CD8+ T cell depletion, there was no change in the tumor growth rate between B4galt3 KO and WT mice, although the tumor growth rate was suppressed in B4galt3 KO mice with isotype antibody." (PMID 37901252, 2023).
B4GALT3 also shares sentences with these, for which no sentence is quoted: colon carcinoma (2 papers); adenoid cystic carcinoma (1); breast adenocarcinoma (1); melanoma (1); mesothelioma (1); osteoporosis (1); sarcoma (1); serous ovarian cancer (1).